MIR181D (microRNA 181d)
Synonyms: hsa-mir-181d; MIRN181D; mir-181d
Gene: MicroRNA gene on chromosome 19 (13,874,875 to 13,875,011, forward strand). Ensembl gene ENSG00000207585.
Diseases named in the same sentence as MIR181D in open-access papers:
MIR181D is named in the same sentence as 1 disease in open-access papers, as found by Europe PMC text mining. Sharing a sentence is not in itself a finding about the gene and the disease.
MIR181D shares sentences with these, for which no sentence is quoted: pancreatic adenocarcinoma (1 paper).